UBE2L6 (ubiquitin conjugating enzyme E2 L6)
Description:
Catalyzes the covalent attachment of ubiquitin or ISG15 to other proteins. Promotes ubiquitination and subsequent proteasomal degradation of FLT3.
Synonyms: RIG-B; UBCH8
Tractability: Small molecule: a structure with a bound ligand is known. PROTAC: UniProt records ubiquitination sites on it; ubiquitination databases record sites on it; its protein half-life has been measured.
Target class: Enzyme; Transferase
Gene: Protein-coding gene on chromosome 11 (57,551,656 to 57,568,284, reverse strand). Ensembl gene ENSG00000156587.
Subcellular location (Human Protein Atlas): Cytosol
Pathways (Reactome):
Immune System: Antigen processing: Ubiquitination & Proteasome degradation; DDX58/IFIH1-mediated induction of interferon-alpha/beta; ISG15 antiviral mechanism; Modulation of host responses by IFN-stimulated genes; Negative regulators of DDX58/IFIH1 signaling; PKR-mediated signaling
DNA Repair: Termination of translesion DNA synthesis
Disease: RSV-host interactions
Metabolism of proteins: Amyloid fiber formation
Gene Ontology:
Molecular function: ISG15 conjugating enzyme activity; ISG15 transferase activity; protein binding; ubiquitin conjugating enzyme activity; ubiquitin-protein transferase activity; ubiquitin-like protein transferase activity
Biological process: innate immune response; ISG15-protein conjugation; protein modification process; protein polyubiquitination; ubiquitin-dependent protein catabolic process; protein modification by small protein conjugation; protein ubiquitination
Cellular component: cytoplasm; cytosol; nucleoplasm
Genetic constraint (gnomAD): Loss-of-function variants: 9 observed, 14.28 expected, observed/expected ratio (o/e) 0.63, 90% interval 0.38 to 1.1. The upper end of that interval is the gene's LOEUF score, 1.1, which puts it in group 4 of 6, group 1 being the genes least tolerant of losing a copy. Missense variants: 196 observed, 205.94 expected, observed/expected ratio (o/e) 0.95, 90% interval 0.85 to 1.07. Synonymous variants: 74 observed, 85.98 expected, observed/expected ratio (o/e) 0.86, 90% interval 0.71 to 1.04.
Homologues: Orthologues: chimpanzee UBE2L6 (100% identical), macaque UBE2L6 (92% identical), rabbit UBE2L6 (80% identical), pig UBE2L6 (78% identical), mouse Ube2l6 (76% identical), rat Ube2l6 (74% identical), dog UBE2L6 (71% identical), guinea pig UBE2L6 (66% identical), Drosophila melanogaster Ubc10 (51% identical), Drosophila melanogaster Ubc84D (50% identical), Caenorhabditis elegans ubc-18 (47% identical), Drosophila melanogaster CG17030 (37% identical), and 2 more. Paralogues in human: UBE2L5 (55% identical), UBE2L3 (52% identical), UBE2D4 (38% identical), UBE2D1 (37% identical), UBE2D2 (37% identical), UBE2D3 (35% identical), UBE2E1 (35% identical), UBE2E2 (34% identical), UBE2E3 (33% identical), UBE2Q2 (20% identical), UBE2QL1 (20% identical), UBE2Q1 (18% identical).
Diseases named in the same sentence as UBE2L6 in open-access papers:
UBE2L6 is named in the same sentence as 49 diseases in open-access papers, as found by Europe PMC text mining. Sharing a sentence is not in itself a finding about the gene and the disease. The quoted sentences say what the papers report.
viral infection (6 papers, 2021 to 2025). "Our results with SINV infection also revealed different inhibitory mechanisms, with some proteins targeting the early stages of virus infection (e.g. UBE2L6), and others participating throughout the course of infection (e.g. EPSTI1)." (PMID 40204275, 2025). "The high expression of several interferon-induced viral-response genes (e.g. Bst2, Ifitm3, Ube2l6, and Rnf213) in the control ‘interferon’ cluster might point to a state of general surveillance for viral infection at baseline." (PMID 34939923, 2021). "UBE2L6, the ISG15 E2 transferring enzyme, was detected to be fivefold more abundant after viral infection." (PMID 35281454, 2022). "Finally, dSpace analysis identified several genes (CCL2, OASL, CASP7, TMEM123, MAFB, VRK2, UBE2L6, NAPA) higher in patients with mild viral infection than those with severe viral infection or HCs." (PMID 33765435, 2021). "In contrast, UBE2L6 overexpression did not affect RIG-I and MDA5 expression in the absence of viral infection or NSP5 plasmid transfection, even when UBE2L6 was overexpressed." (PMID 40611336, 2025).
cervical cancer (5 papers, 2020 to 2025). A primary or metastatic malignant neoplasm involving the cervix. "UHRF1 acts as an oncogene in various cancers, including melanoma, and downregulates UBE2L6 in cervical cancer." (PMID 36906655, 2023). "UHRF1 regulates UBE2L6 gene expression by promoting its hypermethylation in cervical cancer cells to induce apoptosis." (PMID 33568199, 2021). "Among the four protective genes, UBE2L6 gene, encoding the ISG15 (IFN‐stimulated gene 15)‐conjugating enzyme UbcH8, was found to be correlated with apoptosis of cervical cancer." (PMID 32902917, 2020). "UBE2L6 enhances the binding of ISG15 to cellular proteins and promotes apoptosis in cervical cancer cells." (PMID 40990020, 2025).
breast carcinoma (4 papers, 2017 to 2023). "A previous study evaluated the effects of silencing either ISG15 or UBE2L6 on drug sensitivity in breast cancer cells." (PMID 28186990, 2017).
melanoma (4 papers, 2017 to 2024). A malignant, usually aggressive tumor composed of atypical, neoplastic melanocytes. "We also analyzed TCGA melanoma data, finding a correlation between low UBE2L6 mRNA expression and poor melanoma survival (p < 0.0001)." (PMID 36906655, 2023). "Further to examine UBE2L6 in human melanoma, we performed immunohistochemical (IHC) staining on 19 pigmented and 20 non-pigmented human melanomas." (PMID 36906655, 2023). "IHC staining of UHRF1 expression in human melanomas showed that highly pigmented cells exhibiting increased UBE2L6 and decreased EZH2 also had low UHRF1 expression." (PMID 36906655, 2023). "To understand UBE2L6 methylation, we focused on the RING E3 ubiquitin ligase UHRF1, previously shown to downregulate UBE2L6 and promote melanoma cell proliferation." (PMID 36906655, 2023). "To evaluate functional consequences of UBE2L6-EZH2 interactions in melanoma, we developed stable UBE2L6-WT-overexpressing pigmented 28:B4:F3 and IGR37 cells." (PMID 36906655, 2023). "Although we found that DZNep reduces EZH2 in melanoma by inducing UBE2L6 expression, its short half-life and broad effects on ubiquitination hinder clinical application." (PMID 36906655, 2023). "Here, we report UBE2L6 as an E2 ubiquitin-conjugating enzyme for EZH2 that regulates EZH2 abundance in melanoma cells." (PMID 36906655, 2023). "Recently, UBE2L6 was shown to be a tumor-suppressor and a prognostic marker in melanoma." (PMID 36906655, 2023). "Alternatively, other UBE2L6 targets may regulate melanoma metastasis." (PMID 36906655, 2023). "Accordingly, melanoma cell viability and invasiveness were promoted by overexpression of EZH2-K381R in UBE2L6-overexpressing cells." (PMID 36906655, 2023). "5’-Aza induced an 80% decline in UBE2L6 CpG island methylation spanning −582 to −378 from the transcription start site, increased UBE2L6, reduced EZH2, and impaired viability in multiple melanoma cell lines." (PMID 36906655, 2023). "We focused on the potential prognostic value of EDN3, CLEC4E, SRPX2, KIR2DL4, UBE2L6, and IFIT2 as immune scores for melanoma patients." (PMID 34660598, 2021). "The IHC staining results showed that Ube2L6, SRPX2, and IFIT2 were expressed at higher levels, while CLEC4E, END3, and KIR2DL4 were expressed at lower levels in 25 melanoma specimens." (PMID 34660598, 2021). "According to immunohistochemistry staining results, Ube2L6, SRPX2, and IFIT2 were expressed at higher levels, while CLEC4E, END3, and KIR2DL4 were expressed at lower levels in 25 melanoma specimens." (PMID 34660598, 2021). "Our studies extend understanding of this oncoprotein by demonstrating UHRF1/UBE2L6/UBR4-mediated EZH2 promotion to enhance LPC phenotypes and disease progression in melanoma, providing a mechanism as to how higher levels of EZH2 are associated with late-stage disease." (PMID 36906655, 2023). "As endogenously ubiquitinated EZH2 was undetectable by LC-MS in all tested melanoma cells (data not shown), we assessed Ube2l6-WT overexpressing B16-F10 cells, detecting Ezh2 ubiquitination at residue K376." (PMID 36906655, 2023). "Tumor-suppressive and anti-metastatic roles of UBE2L6 in vivo have not been described, and we found are mediated in melanoma by the ubiquitin-conjugating function of UBE2L6, working cooperatively with the E3 ligase UBR4, to induce EZH2 ubiquitination and protein degradation." (PMID 36906655, 2023).
COVID-19 (3 papers, 2020 to 2023). A disease caused by infection with severe acute respiratory syndrome coronavirus 2. "Therefore, examining the expression features of LCN2, STAT1 and UBE2L6 in different clinical contexts such as age, gender and smoking status could help us learn more about the pathogenesis of COVID-19 in different populations." (PMID 33242255, 2020). "The interferon (IFN)-stimulated 15 KDa protein (ISG15) had the largest increase in serum of COVID-19 patients, followed by several other IFN-induced proteins, such as ILF2, MX1, ISG20, LAP3, and UBE2L6." (PMID 37739942, 2023).
esophageal cancer (3 papers, 2017 to 2020). A primary or metastatic malignant neoplasm involving the esophagus. "Reportedly, ISG15 and UBE2L6 were identified as negative regulators of autophagy in esophageal cancer cells." (PMID 31309113, 2019). "In this study, we have identified ISG15 and UBE2L6 as negative regulators of autophagy in esophageal cancer cells." (PMID 28186990, 2017). "Here, with endogenous expression in esophageal cancer cells, we report the opposite effect; knockdown of ISG15 or UBE2L6 promotes autophagy." (PMID 28186990, 2017).
acute myeloid leukemia (2 papers, 2020 to 2025). Acute myeloid leukemia (AML) is a group of neoplasms arising from precursor cells committed to the myeloid cell-line differentiation. "Through gene expression analyses in a cohort of 98 acute myeloid leukemia (AML) patient samples and in primary neutrophils from healthy donors, we found that UBE2L6 gene expression is reduced in primary AML cells compared with normal mature granulocytes." (PMID 31820845, 2020). "Additionally, studies have demonstrated reduced expression of UBE2L6 in primary acute myeloid leukemia (AML) cells, where silencing UBE2L6 inhibits ATRA-induced ISG15 conjugation, thus impairing isgylation and hindering AML cell differentiation." (PMID 40990020, 2025).
gastric cancer (2 papers, 2017 to 2023). A primary or metastatic malignant neoplasm involving the stomach. "We interrogated a publically available database to see if we could identify a relationship between expression of UBE2L6 or ISG15 and overall survival in gastric cancer." (PMID 28186990, 2017). "In this study, five crucial immunophenotype‐related molecules (WARS, UBE2L6, GZMB, BATF2, and LAG‐3) in the TME are determined in five public gastric cancer (GC) datasets (n = 1426) and an in‐house sequencing dataset (n = 79)." (PMID 36998102, 2023).
Hypertension (2 papers, 2023 to 2026). The presence of chronic increased pressure in the systemic arterial system. "By applying this novel approach, we not only confirmed well-established biomarkers for diseases such as hypertension (UBE2L6) and leukemia (LRCH4) but also identified novel protein candidates." (PMID 41724807, 2026).
leukemia (2 papers, 2025 to 2026). A malignant (clonal) hematologic disorder, involving hematopoietic stem cells and characterized by the presence of primitive or atypical myeloid or lymphoid cells in the bone marrow and the blood. "HHT and gilteritinib can upregulate Ubiquitin Conjugating Enzyme E2 L6 (UBE2L6) together, promoting the degradation of Mcl-1 through the ubiquitin-proteasome pathway, and bring an effective drug target for FLT3-ITD mutated leukemia." (PMID 39949739, 2025).
lymph node metastasis (2 papers, 2015 to 2021). "As seen with ISG15, UBE2L6 mRNA expression levels negatively correlated with survival in patients with cancer that had spread to the lymph nodes whereas the correlation was lost in patients without lymph node metastasis." (PMID 34556814, 2021).
nasopharyngeal carcinoma (2 papers, 2015 to 2021). A carcinoma arising from the nasopharyngeal epithelium. "Other studies have shown that UBE2L6 is involved in the lipolysis process in nasopharyngeal carcinoma and associated with its poor prognosis." (PMID 34773365, 2021). "We identified the UBE2L6 gene, encoding the ISG15-conjugating enzyme UbcH8, as one gene significantly downregulated by promoter hypermethylation in nasopharyngeal carcinoma (NPC)." (PMID 26506425, 2015).
sarcoid (2 papers, 2021 to 2024). "The induced expression levels of the individual genes FCGR1B, GBP1, IFIT2, SERPING1, and UBE2L6 could discriminate between patients with sarcoidosis and TB with a maximum Youden's index >0.80 and corresponding sensitivity >88 % and specificity >89 %." (PMID 39309852, 2024). "Compared to HCs, serum from patients with sarcoidosis significantly (p < 0.05) induced the expression of FCGR1B and IFIT2, whereas serum from patients with TB significantly (p < 0.05) reduced the expression of GBP1, SERPING1, and UBE2L6 compared to HCs." (PMID 39309852, 2024).
tuberculosis (2 papers, 2024 to 2026). A chronic, recurrent infection caused by the bacterium Mycobacterium tuberculosis. "UBE2L6, an E2 ubiquitin-conjugating enzyme, has been identified as a biomarker for active tuberculosis, displaying heightened expression in the whole blood of tuberculosis patients." (PMID 38680421, 2024). "UBE2L6 and miR-146a-5p appear to serve as biomarkers for tuberculosis." (PMID 41457557, 2026). "Notably, cg11554335, situated on the UBE2L6 gene, exhibits low methylation in tuberculosis (TB) and elevated gene expression." (PMID 38680421, 2024).
acute promyelocytic leukemia (1 paper, 2020). An aggressive form of acute myeloid leukemia (AML), characterized by arrest of leukocyte differentiation at the promyelocyte stage, due to a specific chromosomal translocation t(15;17) in myeloid cells. "Previous gene expression studies in acute promyelocytic leukemia (APL) cells showed that all‐trans‐retinoic acid (ATRA) altered the expression of many genes, including UBE2L6 (200‐fold) and other members of the ISGylation pathway." (PMID 31820845, 2020).
Ataxia (1 paper, 2017). Ataxia refers to impaired coordination of voluntary muscle movement. "AHR is involved in the regulation of biological responses to planar aromatic hydrocarbons; UBE2L6 targets abnormal or short-lived proteins for degradation; and PAFAH1B3 functions in brain development and is associated with mental retardation, ataxia, and atrophy of the brain." (PMID 28178176, 2017).
atherosclerosis (1 paper, 2024). A disease characterized by the build-up of fatty material and calcium deposition in the arterial wall resulting in partial or complete occlusion of the arterial lumen. "The expression of MX1 and UBE2L6 was 507.22 ± 342.56 and 96.99 ± 49.92 in the HC+STZ group, respectively, which was significantly higher than others and may be linked to the severity of hyperglycaemia-related atherosclerosis." (PMID 38406276, 2024).
esophageal squamous cell carcinoma (1 paper, 2017). Esophageal squamous cell carcinoma (ESCC) is a type of esophageal carcinoma (EC) that can affect any part of the esophagus, but is usually located in the upper or middle third. "Significant upregulation of UBE2L6 was reported in prostate cancer and esophageal squamous cell carcinoma when compared to corresponding non-malignant tissues." (PMID 28186990, 2017).
HIV-1 infection (1 paper, 2025). The type species of lentivirus and the etiologic agent of acquired immunodeficiency syndrome (AIDS). "While UBE2L6 is a known ISG15 ligase in innate immune response, UBE2J2 has no documented role in HIV-1 infection." (PMID 40204275, 2025).
hyperglycaemia (1 paper, 2024). "In contrast, the expression of MX1 and UBE2L6 in the other group with stable hyperglycaemia was only 31.10 ± 19.21 and 28.21 ± 14.30, similar to that in the control group (p < 0.05 and p < 0.05, respectively)." (PMID 38406276, 2024). "The axis of hyperglycaemia-higher MX1 and UBE2L6 expression-serious AS was present, which also highlighted the importance of MX1 and UBE2L6 in the comorbidity of DM and AS." (PMID 38406276, 2024).
Listeria infection (1 paper, 2015). "We found that UBE1L (E1), UBE2L6 (E2), HERC5 and TRIM25 (E3s) mRNA are all significantly upregulated following Listeria infection, as is the deconjugating enzyme USP18." (PMID 26259872, 2015).
metastatic melanoma (1 paper, 2023). A melanoma that has spread from its primary site to another anatomic site. "Interestingly, a mild decline (p = 0.0575) was noted in cytosolic UBE2L6 from early stage to metastatic melanoma, inversely correlated with EZH2." (PMID 36906655, 2023).
oesophageal cancer (1 paper, 2024). "Of those factors identified, UBE2L6 usually acts as a ubiquitin-conjugating enzyme and was reported to be related to lipid metabolism, apoptosis of Mycobacterium tuberculosis-infected macrophages, and autophagy attenuation in oesophageal cancer cells." (PMID 38406276, 2024).
renal carcinoma (1 paper, 2018). A carcinoma arising from the epithelium of the renal parenchyma or the renal pelvis. "Small RNA-induced knockdown of GAPDH in renal carcinoma cells was accompanied by increased expression of IFI6, OAS3, and UBE2L6." (PMID 30253781, 2018).
infection (11 papers, 2012 to 2025). The state of being infected such as from the introduction of a foreign agent such as serum, vaccine, antigenic substance or organism. "Our data demonstrates that UBE2L6 plays a substantive role in SVA infection of host cells through posttranslational modification pathways." (PMID 33104725, 2020). "In this study, we demonstrated that UBE2L6 participated in the process of SVA infection and ubiquitinated the 3D protein." (PMID 33104725, 2020). "Many studies have also implicated UBE2L6 and ISG15 as critical components of the innate immune response to pathogen infection." (PMID 28186990, 2017). "As FGA/NA d1d and FGA/NA a5c differ by only three amino-acid substitutions in the E protein, we will investigate further the modulation of the Ube2l6 protein and its interaction with the replication complex during infection with the recombinant viruses generated in this study." (PMID 22530074, 2012). "UBE2L6 protein expression was up-regulated following PRRSV infection, with levels peaking at 36 and 48 h post-infection (hpi)." (PMID 40611336, 2025). "Our data demonstrate that UBE2L6 ubiquitinates SVA 3D, thereby facilitating SVA infection." (PMID 33104725, 2020). "In order to assess whether UBE2L6 and TRIM25 are induced as rapidly as ISG15 at the protein level, we monitored their expression by immunoblot at 3 hr post infection." (PMID 26259872, 2015).